CERK (ceramide kinase)
Description:
Catalyzes specifically the phosphorylation of ceramide to form ceramide 1-phosphate. Acts efficiently on natural and analog ceramides (C6, C8, C16 ceramides, and C8-dihydroceramide), to a lesser extent on C2-ceramide and C6-dihydroceramide, but not on other lipids, such as various sphingosines. Shows a greater preference for D-erythro isomer of ceramides. Binds phosphoinositides.
Synonyms: hCERK; LK4; KIAA1646; FLJ23239; dA59H18.3; DKFZp434E0211; FLJ21430; dA59H18.2
Tractability: Antibody: UniProt places it where antibodies can reach, with high confidence; its Gene Ontology location is reachable by antibodies, with high confidence. PROTAC: ubiquitination databases record sites on it.
Target class: Enzyme; Transferase
Gene: Protein-coding gene on chromosome 22 (46,684,410 to 46,738,267, reverse strand). Ensembl gene ENSG00000100422.
Subcellular location: Cell membrane; Golgi apparatus, trans-Golgi network
Subcellular location (Human Protein Atlas): Vesicles
Pathways (Reactome):
Metabolism: Glycosphingolipid biosynthesis
Gene Ontology:
Molecular function: ceramide kinase activity; magnesium ion binding; protein binding; kinase activity
Biological process: ceramide metabolic process; glycosphingolipid biosynthetic process
Cellular component: cytoplasm; cytoplasmic side of trans-Golgi network membrane; membrane; plasma membrane; Golgi apparatus
Genetic constraint (gnomAD): Loss-of-function variants: 30 observed, 49.08 expected, observed/expected ratio (o/e) 0.61, 90% interval 0.46 to 0.83. The upper end of that interval is the gene's LOEUF score, 0.83, which puts it in group 3 of 6, group 1 being the genes least tolerant of losing a copy. Missense variants: 555 observed, 573.11 expected, observed/expected ratio (o/e) 0.97, 90% interval 0.9 to 1.04. Synonymous variants: 261 observed, 232.38 expected, observed/expected ratio (o/e) 1.12, 90% interval 1.01 to 1.24.
Homologues: Orthologues: macaque CERK (98% identical), chimpanzee CERK (96% identical), dog CERK (88% identical), pig CERK (85% identical), rat Cerk (85% identical), mouse Cerk (84% identical), rabbit CERK (81% identical), guinea pig CERK (77% identical), tropical clawed frog cerk (61% identical), zebrafish cerk (53% identical), Drosophila melanogaster Cerk (35% identical), Caenorhabditis elegans cerk-1 (28% identical), and 3 more. Paralogues in human: CERKL (28% identical), SPHK2 (20% identical), SPHK1 (17% identical), AGK (17% identical).
Diseases named in the same sentence as CERK in open-access papers:
CERK is named in the same sentence as 53 diseases in open-access papers, as found by Europe PMC text mining. Sharing a sentence is not in itself a finding about the gene and the disease. The quoted sentences say what the papers report.
breast cancer (23 papers, 2017 to 2025). A primary or metastatic malignant neoplasm involving the breast. "High expression of CERK in lymph node positive and late-stage cancer patients and its association to poor OS further strengthen its potential as a prognostic biomarker in breast cancer patients." (PMID 36309544, 2022). "Consistently, in human patients, the upregulation of CERK expression is associated with an elevated risk of breast cancer recurrence in women." (PMID 35565311, 2022). "High expression of CERK was also associated with poor OS in nodal positive and late-stage breast cancer patients." (PMID 36309544, 2022). "Elevated CERK expression is associated with an increased risk of recurrence in women with breast cancer." (PMID 34766135, 2021). "In particular, CerK has been found overexpressed in breast cancer and its level is associated with poor prognosis." (PMID 34209043, 2021). "Studies from patient biopsies revealed that increased CerK expression is associated with an elevated risk of tumor recurrence in women with breast cancer." (PMID 34357010, 2021). "Among the genes activated by ZNF518B, CERK is associated with highly aggressive human breast cancer and GINS1 expression correlates with proliferation of breast cancer cells and with poor prognosis in hepatocellular carcinoma." (PMID 33801071, 2021). "Previous studies using cell models and publicly available microarray data show that elevated CERK expression is linked with metastatic breast cancer and increased risk of recurrence in patients with breast cancer." (PMID 33430896, 2021). "Gene expression profiles from more than 2200 patients revealed that elevated CERK expression is associated with an increased risk of recurrence in women with breast cancer." (PMID 29269995, 2017). "Furthermore, a study included 2200 breast cancer patients in a gene expression analysis of CerK, and found an association of increased CerK expression with increased risk of cancer recurrence." (PMID 32092937, 2020). "CERK has also been found to be overexpressed in breast cancer and associated with poor prognosis." (PMID 29269995, 2017). "Analysis of gene expression profiles, from more than 2200 patients with breast cancer, revealed that CERK expression was associated with an increased risk of recurrence in women with breast cancer, suggesting that targeting this pro-survival enzyme may be highly beneficial to overcome this disease." (PMID 35008391, 2022). "Additionally, CerK correlates with a higher risk of tumor recurrence in women with breast cancer." (PMID 32092937, 2020). "Regarding breast cancer, CerK was shown to be upregulated in metastatic breast cancer cells and is a common therapeutic target for both triple-positive and triple-negative breast cancer." (PMID 40943293, 2025). "CerK was also associated with a poor prognosis in breast cancer patients, and endocrine therapy-resistant breast cancer cells were more sensitive to CerK inhibition than therapy-sensitive breast cancer cells." (PMID 40943293, 2025). "Accumulating research has shown that CERK and its metabolite C1P play complex regulatory roles in several kinds of tumors, such as leukemia, breast cancer, lung cancer, neuroblastoma, pancreatic cancer, and prostate cancer." (PMID 38556546, 2024). "To establish the role of sphingolipids in breast cancer metastasis, we analyzed the associations of MMP-2 and MMP-9 with SPHK1 and CERK expression." (PMID 36309544, 2022). "The product of CERK, C1P, can inhibit de novo ceramide production, an important consequence that specifically promotes ET-resistant breast cancer cell survival." (PMID 35625985, 2022). "NVP-231 treatment inhibited the growth of HCI-011-FR significantly more than HCI-011, further supporting our finding that ET-resistant breast cancer models are more sensitive to CERK inhibition than ET-sensitive models." (PMID 35625985, 2022). "A significant positive correlation was also observed between CERK levels and Ki67 index of breast cancer patients." (PMID 36309544, 2022).
breast cancer (continued). "Therapeutically, targeting CERK can therefore be a potential treatment modality in women with ER+ breast cancer that develop resistance to standard ETs." (PMID 35625985, 2022). "By targeting CERK and reducing the level of C1P, it is possible to exploit the sphingolipid profile of tamoxifen-resistant breast cancer by inducing ceramide-dependent cell death." (PMID 35625985, 2022). "CERK has also been reported earlier to promote tumor cell growth, survival and mammary tumor recurrence." (PMID 36309544, 2022). "Although CerK can regulate Rac1 activity and inhibit lamellipodium formation in A549 cells, it can promote migration in breast cancer." (PMID 35965565, 2022). "High expression of CERK has been reported to contribute to cell migration and invasion in metastatic breast cancer cells." (PMID 36309544, 2022). "Another study has shown that CERK expression in breast cancer cells promotes migration and invasion via the PI3K/Akt pathway." (PMID 35565311, 2022). "Significant high level of CERK was observed in ER Positive (*p = 0.049), nodal positive (*p = 0.047) and late-stage breast cancer patients (*p = 0.037)." (PMID 36309544, 2022). "Above studies therefore, reinforce the significance of CERK in discriminating the tumor tissue from adjacent normal tissues in breast cancer patients." (PMID 36309544, 2022). "Upon perturbing the sphingolipid pathway with small molecule inhibitors of key enzymes, we identified that CERK is essential for tamoxifen-resistant breast cancer cell survival, as well as a fulvestrant-resistant PDxO." (PMID 35625985, 2022). "We observed a significant upregulation in the expression of CERK in ER positive, nodal positive and late-stage breast cancer patients." (PMID 36309544, 2022). "CerK activity is required in the proliferation of neuroblastoma cells, of breast cancer cells, and of Kaposi sarcoma stem cells." (PMID 33450869, 2021). "Apart from chemoresistance, we showed that CERK promoted TNBC migration, which is in line with the findings of a recent study on the contribution of CERK to migration and invasion in metastatic breast cancer cells." (PMID 33430896, 2021). "Our work agrees with and further extends these previous studies by demonstrating that CERK upregulation is associated with chemoresistance in patients with TNBC, the most aggressive subtype of breast cancer." (PMID 33430896, 2021). "Sphingolipids were identified in breast cancer patients, and genes related to metabolism, such as CERK, SPHK1, and SGMS1, were verified by a TCGA cohort." (PMID 34549263, 2021). "Various studies have reported the functional role of CERK in breast cancer progression and recurrence." (PMID 33430896, 2021). "Although our data focus on the effect of CERK upregulation on chemotherapeutic responses in TNBC, it is possible that CERK also accounts for treatment resistance among other subtypes of breast cancer or even other cancers." (PMID 33430896, 2021). "In metastatic breast cancer cells, CerK is upregulated and contributes to the migration and invasion through PI3K/Akt/Rho kinase activation." (PMID 33450869, 2021). "Altogether, our data demonstrate for the first time that CerK promotes migration and invasion of metastatic breast cancer cells and that targeting of CerK has potential to counteract metastasis in breast cancer." (PMID 32092937, 2020). "The present study is the first report on the levels of ceramide phosphates and CERK expression in breast cancer patients and clinical correlations of ceramide phosphates with Ki67 index, making it a pioneer study in this field." (PMID 32170160, 2020). "Using CerK knockdown and overexpression in our breast cancer cell lines, we found that, in addition to PI3K and ROCK, CerK also activates Akt, another major driver of malignancy." (PMID 32092937, 2020).
breast cancer (continued). "This suggests that CerK is a potent driver of metastasis in breast cancer and is in line with recent findings that CerK positively regulates migration and invasion of pancreatic cancer cells." (PMID 32092937, 2020). "In MCF-7 breast cancer and NCI-H358 lung cancer cells, the CerK inhibitor NVP-231 caused a concentration-dependent decrease in cell viability and induced apoptosis." (PMID 32722626, 2020). "In conclusion, we demonstrate for the first time that CerK expression and activity correlate well with the metastatic potential of breast cancer cells and are enhanced in cells after dissemination to distant sites." (PMID 32092937, 2020). "CERK has also been reported earlier to promote tumor cell growth, survival and mammary tumor reccurrence." (PMID 32170160, 2020). "Studies from the same group along with others supported that CERK expression is associated with high grade aggressive basal and HER2+ breast cancer subtypes." (PMID 29269995, 2017). "This study was further validated in a mouse model and supported that CERK/C1P is important for breast cancer recurrence." (PMID 29269995, 2017). "The involvement of CerK/C1P in the promotion of cell survival was also demonstrated by Mitra and co-workers using human A549 lung cancer cells and by Payne and co-workers who showed that CerK promoted breast cancer cell survival and mammary tumor recurrence." (PMID 40943293, 2025). "Interestingly, CERK has been identified as a regulator of tamoxifen resistance in ER+ breast cancer." (PMID 38139092, 2023). "Asking whether this alternative sphingolipidome exposes unique vulnerabilities that can be exploited to treat tamoxifen-resistant breast cancers, we found that tamoxifen-resistant cells are uniquely dependent on CERK." (PMID 35625985, 2022). "Moreover, inhibition of CERK counteracted chemoresistance in the breast cancer cells through a mechanism involving activation of the Ras/ERK, PI3K/Akt/mTOR, and RhoA pathways." (PMID 35008391, 2022). "The fact that CERK was spontaneously upregulated in different oncogene-derived mammary tumor models rapidly, following withdrawal of chemo/Her2/neu inhibitor therapy strongly indicated the role of CERK/C1P in generation of apoptosis resistant tumor cells that are disseminated from the primary site." (PMID 36139656, 2022). "Consequently, ET-resistant breast cancer models have a unique dependence on CERK as its activity can inhibit de novo ceramide production." (PMID 35625985, 2022). "CERK was shown to be upregulated following HER2/neu pathway inhibition in breast cancer cells." (PMID 33430896, 2021). "The levels of ceramide kinase (CERK) was determined in breast cancer patients." (PMID 33430896, 2021). "CerK is particularly relevant in lung and breast cancer cell proliferation and dissemination." (PMID 34357010, 2021). "Furthermore, upregulation of CerK is profoundly important for the development of human breast cancer." (PMID 34357010, 2021). "CERK is required for mammary tumor recurrence following HER2/neu pathway inhibition." (PMID 34766135, 2021). "The association of CERK expression with poor clinical outcome is not limited to ER-negative breast cancer, but also found in other aggressive subtypes of breast cancer, including HER2+, basal-like, or high-grade breast cancer." (PMID 33430896, 2021). "In this model system, we show a clear correlation between CerK expression, activity, and metastatic potential of the cells, and we demonstrate that CerK substantially contributes to breast cancer migration and invasion by activation of the PI3K/Akt and the Rho kinase pathways." (PMID 32092937, 2020). "Here, we investigated the involvement of CerK in the migration and invasion of breast cancer cells in vitro using the breast cancer cell line MDA-MB-231 and two sublines thereof derived from either lung metastasis (4175) or bone metastasis (1833) in immuno-deficient mice." (PMID 32092937, 2020).
breast cancer (continued). "CerK is up-regulated in metastatic breast cancer cells, and plays a role in migration and invasion." (PMID 32722626, 2020). "CERK promotes tumor cell survival and mammary tumor recurrence." (PMID 29269995, 2017). "Hence, CERK can be a potential target for multiple breast cancer subtypes." (PMID 36139656, 2022). "Together with our data that CerK is implicated in migration and invasion by activating PI3K and Akt signaling in metastatic cells, this warrants further investigation to better understand the pro-malignant function of CerK and to assess the therapeutic potential of CerK targeting in breast cancer." (PMID 32092937, 2020). "A correlation between CERK and SPHK1 with metastasis and/or drug resistance in breast cancer has been demonstrated." (PMID 38139092, 2023). "Previously, we identified the high levels of sphingolipids, ceramide phosphates and sphingosine phosphates, and the genes involved in their synthesis, CERK and SPHK1, in breast cancer patients." (PMID 36309544, 2022). "Similar to the CERK, the levels of SPHK1 were found to be significantly high in patients with nodal metastasis and advanced stage of breast cancer." (PMID 36309544, 2022). "In the present study, we measured the expression of MMP-2 and MMP-9 in breast cancer patients and determined their correlations with SPHK1 and CERK in local as well as TCGA cohort." (PMID 36309544, 2022). "However, when MCF-7 breast cancer cells are treated by delivering a ceramide kinase inhibitor into cellular mitochondria, the generated ceramide arrested MCF-7 at the G2/M phase and may have caused cell apoptosis by increasing DNA fragmentation and causing caspase-3 and caspase-9 cleavage." (PMID 35328500, 2022). "CERK overexpression has been shown to promote triple-negative breast cancer (TNBC) growth and migration and confer chemotherapy resistance to breast cancer cell lines." (PMID 35565311, 2022). "In metastatic breast cancer cells, PI3K, Akt, mTOR, and RhoA were demonstrated to be responsible for migration regulation by CERK." (PMID 33430896, 2021). "The activation of multiple oncogenic pathways as a result of CERK overexpression correlates well with the positive regulatory roles of CERK in TNBC and other types of breast cancer cells." (PMID 33430896, 2021). "This supports the conclusion that CerK activates PI3K/Akt signaling, which is crucial for the here reported migration and invasion of metastatic breast cancer cells." (PMID 32092937, 2020). "CERK appears to be playing different roles in more aggressive metastatic breast cancer cell lines versus non-metastatic cell lines targeting cell migration and cell proliferation in a context-dependent manner." (PMID 36139656, 2022). "CERK expression was found to be higher in ER negative as compared to ER positive breast cancer (luminal subtypes), and worst prognosis, shorter survival and higher recurrence rate were positively associated to higher CERK expression among ER-negative cancers." (PMID 36139656, 2022). "Here, we focused on differences in CerK expression and activity between high and non-metastatic breast cancer cell lines and investigated the effect of genetic and pharmacologic CerK modulators on cell motility and invasion in vitro." (PMID 32092937, 2020). "However, there is no study defining the significance of CERK among various clinical subgroups in breast cancer." (PMID 36309544, 2022). "However, high CERK expression was related to poor OS in patients with lymph node metastasis (*p = 0.023) and late-stage breast cancer patients (*p = 0.040)." (PMID 36309544, 2022). "In addition, CerK expression was found to be higher in estrogen receptor (ER)-negative than in ER-positive breast cancer, and within the ER-negative subgroup of patients, those with highest CerK expression had the worst prognosis and the shortest survival." (PMID 32092937, 2020).
breast cancer (continued). "Previously, it was shown that CerK expression is higher in estrogen receptor (ER) negative than in ER positive breast cancer tissue, and that within the ER negative subgroup of patients, those with highest CerK expression had the worst prognosis and the shortest survival." (PMID 32092937, 2020). "Importantly, CERK was not highly connected nor was highly between in the network, but it was functionally close with other candidates, indicating it to be playing major role in maintaining the regulatory interactions during breast cancer." (PMID 36309544, 2022). "However, in our breast cancer model, neither inhibition of CerK with NVP-231 nor CerK knockdown could attenuate PGE2 formation, thus excluding the notion that high PGE2 production in metastatic cells is due to enhanced C1P production by CerK." (PMID 32092937, 2020).